ENSG00000305635 (novel transcript, antisense to BAX and FTL)
Gene: Long non-coding RNA gene on chromosome 19 (48,949,933 to 48,965,953, reverse strand). Ensembl gene ENSG00000305635.
Gene Ontology:
Biological process: response to iron ion